SESN2 (sestrin 2)
Diseases named in the same sentence as SESN2 in open-access papers (continued):
Sharing a sentence is not in itself a finding about the gene and the disease.
melanoma (11 papers, 2018 to 2025). A malignant, usually aggressive tumor composed of atypical, neoplastic melanocytes. "Sestrin 2 has also been implicated in cold atmospheric plasma (CAP)-induced apoptosis of melanoma cells by activating the sestrin 2/nitric oxide synthase (iNOS) pathway." (PMID 34784907, 2021). "In contrast to Sestrins’ recognised tumour-suppressive function across multiple tissues, SESN2 frequently shows elevated expression in various skin cancers, including melanomas and squamous cell carcinomas, acting as an oncogene to promote skin carcinogenesis." (PMID 40361504, 2025). "In the majority of studies, Sesn2 primarily plays an inhibitory role in cancer, but it has also been reported that Sesn2 promotes the development of cancer, such as pancreatic cancer, liver cancer, and melanoma." (PMID 41614860, 2025). "In human SCC and melanoma cells, sestrin 2 induced chemotherapeutic drug resistance by activating the AKT pathway and regulating PTEN activity." (PMID 34784907, 2021). "Sestrin 2 knockdown facilitated apoptosis induced by vemurafenib and 5-FU in human melanoma cells (A375 and MEL624 lines) and the SCC cell line A431, respectively, and suppressed the growth of A431 and A375 cells xenografted in nude mice." (PMID 34784907, 2021). "Another study demonstrated that sestrin 2 promoted anoikis resistance in melanoma cells and contributed to melanoma metastasis in vivo." (PMID 34784907, 2021). "Both UVB and UVA induce Sesn2 upregulation in melanocytes and melanoma cells suggesting the oncogenic role of Sesn2 in melanoma skin cancer." (PMID 33425907, 2020). "As has been reported in prostate cancer, melanoma and squamous carcinoma, SESN2 serves as an upstream regulator in AKT signaling pathway to maintain cancer cell survival." (PMID 30311444, 2018). "Additionally, another study showed that Sesn2 promotes AKT activation in melanoma and skin squamous carcinoma while exerting oncogenic effects by promoting cell viability under UVB stress and chemotherapy." (PMID 41614860, 2025). "Experiments on melanoma xenografts in mice showed that cancer cells with silenced SESN2 produced smaller tumours, which the authors attributed to increased survival of inoculant cells due to SESN2’s protection from ROS and possibly the activation of pro-survival AKT." (PMID 40361504, 2025). "Along with the increased 4HNE levels, we also found altered expression of Sestrin 2 (SESN2), an evolutionarily conserved protein known to regulate the cellular antioxidant response and the aging process and play a role in tumor suppression, such as melanoma." (PMID 38068996, 2023). "It remains controversial whether sestrin 2 serves as a tumor-suppressing gene or oncogene in lung, liver, colorectal, breast, melanoma, and endometrial cancers." (PMID 34784907, 2021). "Additionally, upregulated Sesn2 may facilitate ECM-detached melanoma cells in anoikis resistance, and Sesn2 mediates anoikis resistance by detoxifying intracellular ROS." (PMID 40331942, 2025). "For example, the knockdown of SESN2 in melanoma cells was followed by elevated oxidative stress levels and increased apoptosis rates, whereas the upregulation of the SESN2 gene exerted a protective role by detoxifying oxidative stress species and disrupting subsequent melanoma formation." (PMID 38068996, 2023). "Upregulation of Sestrin 2- but not Sestrin 3- by MCL1 depletion was observed in a panel of melanoma cell lines, arguing for the generalization of this effect in melanoma cells." (PMID 41326406, 2025). "Sesn2 promotes tumorigenesis and chemo-resistance under Ultraviolet B (UVB) stress and chemo-therapeutics by activating AKT in human squamous cell carcinomas (SCCs) and melanoma cells." (PMID 33425907, 2020). "Sesn2 positively regulates Akt signaling and survival in human squamous cell carcinoma (SCC) and melanoma cells in response to UVB stress and chemotherapeutics, suggesting that Sesn2 may promote tumorigenesis and chemoresistance in SCC and melanoma." (PMID 32010489, 2020).
melanoma (continued). "We additionally confirmed the expression with mRNA levels of key genes after treatment with lj-1-59 in melanoma cells, which indicated that P21, BBC3, SESN2 and GADD45A expression were significantly upregulated, while MCM2, MCM3, MCM4, MCM7 and PKMYT1 were significantly downregulated." (PMID 32021565, 2020). "However, several more recent studies revealed that higher levels of Sesn2 expression are found in melanoma and squamous cell carcinoma compared to noncancerous tissues, and the increased expression was associated with a poorer prognosis." (PMID 41614860, 2025).
bladder cancer (10 papers, 2019 to 2025). "Low expression of SESN2 was also observed in primary invasive bladder cancer tissue and was associated with bladder cancer formation." (PMID 37284849, 2023). "ChlA-F, a derivative of cheliensisin A, and isorhapontigenin, a derivative of stilbene, inhibit the anchorage-independent growth of bladder cancer cells by inducing sestrin-2-dependent autophagy." (PMID 38396629, 2024). "Further, the restoration of a high level of SESN2 was sufficient for promoting autophagy and further mediating the inhibition of an anchorage-independent growth of human bladder cancer cells." (PMID 37284849, 2023). "The two studies presented below have shown the induction of autophagy-dependent anti-cancer effect via upregulating SESN2 protein in human bladder cancer cells." (PMID 37284849, 2023). "After treatment of UMUC3 and T24T bladder cancer cells with ISO, sestrin 2 expression was elevated by activation of the MAPK8/JUN pathway, and activated sestrin 2 induced autophagy and inhibited the growth of bladder cancer cells." (PMID 34784907, 2021). "This study suggests that ISO might act as a promising preventive and/or therapeutic drug against human bladder cancer by modulating SESN2 expression." (PMID 31546746, 2019). "The upregulation of SESN2 expression after ISO treatment occurred via MAPK8-Jun-dependent transcriptional regulation, which provides a novel mechanistic insight into the cytotoxic effect of ISO on bladder cancers." (PMID 31546746, 2019). "Therefore, we preliminarily selected SESN2 as a downstream target regulated by SND1, which has been reported to be downregulated in various cancers and to inhibit bladder cancer progression, but its role in PCa remains unclear." (PMID 40775338, 2025).
glioblastoma (10 papers, 2016 to 2025). The most malignant astrocytic tumor (WHO grade IV). "In glioblastoma, silencing SESN2 in U87 tumour cells sensitised them to ionising radiation (IR), reducing proliferation, and significantly increasing ROS levels." (PMID 40361504, 2025). "Further work demonstrated that SESN2 knockout impaired PDGFRβ degradation via reduced proteasomal activity, distinct from the mechanism observed in glioblastoma." (PMID 40361504, 2025). "Treatment on U87MG glioma cell lines and patient-derived primary S1 glioblastoma cells have seen ATO suppression of miR182-5p subsequently increasing Argonate-2 (AGO2)-gene silencing of Sestrin 2 (SESN2 protein coding gene)." (PMID 36145693, 2022). "Sesn2 (aka Hi95) was identified by microarray in Hif1-independent hypoxia condition of glioblastoma A172 cells and located in chromosome 1p35.3." (PMID 33425907, 2020). "Ionizing radiation has been reported to induce SESN2 expression in glioblastoma cells, but silencing of SESN2 not only increases intracellular oxidative stress but also sensitizes cells to ionizing radiation." (PMID 29662624, 2018). "One study reported that Sesn2 was induced in human glioblastoma U87 cells following ionizing radiation (IR)." (PMID 27453548, 2016). "Overall, the interaction between SESN2 and PDGFRβ in glioblastoma remains incompletely understood, and it is unclear whether PDGFRβ modulation by SESN2 significantly influences glioblastoma progression or reflects a broader regulatory mechanism." (PMID 40361504, 2025). "Puzzlingly, their findings have shown that ATO can also promote antioxidant activities by the upregulation of SESN2 in patient-derived primary S1 glioblastoma (GBM) cells, the U87MG glioma cell line, the human lung adenocarcinoma H1299 cell line and the A549 cell line." (PMID 37284849, 2023). "Ionizing radiation has been reported to induce SESN2 expression in human glioblastoma U87 cells." (PMID 34829679, 2021). "Here we found that ATO could inhibit miR-182-5p expression in patient-derived primary S1 glioblastoma (GBM) cells accompanied by up-regulation of Sestrin-2 (SESN2) mRNA, a known anti-oxidant molecule." (PMID 29662624, 2018). "In glioblastoma and NSCLC cells, SESN2 expression was elevated after irradiation, and SESN2 knockdown sensitized cancer cells to irradiation as well." (PMID 36611970, 2022).
endometrial cancer (9 papers, 2019 to 2025). Primary or metastatic malignant neoplasm involving the endometrium (mucous membrane that lines the endometrial cavity). "Our study provides strong evidence for prognostic significance of SESN2, and its association with mTORC1 pathway and endometrial cancer growth." (PMID 32899752, 2020). "Here, we investigated expression, clinical significance, and underlying mechanisms of SESN2 in endometrial cancer." (PMID 32899752, 2020). "Results showed that high SESN2 expression was associated with significantly decreased overall survival (p = 0.018) and disease-free survival (p = 0.032) in patients with endometrial cancer." (PMID 32899752, 2020). "High SESN2 expression was associated with poor prognosis in endometrial cancer patients, whereas knockdown of SESN2 promoted cell proliferation and migration in endometrial cancer cell lines HEC-1A and Ishikawa." (PMID 32899752, 2020). "Furthermore, the Kaplan–Meier survival analysis suggested that SESN2 could serve as a diagnostic marker for the development of endometrial cancer." (PMID 32899752, 2020). "A study of SESN2 in primary endometrial cancer tissue revealed that SESN2 was upregulated in cancer tissues." (PMID 40361504, 2025). "Xenografts of endometrial cancer also have shown to grow larger and heavier with inhibition of SESN2." (PMID 40361504, 2025). "We have probed the mTORC1-dependent mechanism of SESN2 that suppresses endometrial cancer cells, although further experimental studies would be required to explore the role of SESN2-mediated autophagy in inhibiting endometrial cancer growth and progression." (PMID 32899752, 2020). "Further, the function of SESN2 in endometrial cancer cell migration was evaluated using the wound healing scratch assay." (PMID 32899752, 2020). "In contrast, our results clearly demonstrate upregulation of SESN2 mRNA and protein levels in endometrial cancer tissues." (PMID 32899752, 2020). "The elevated expression of SESN2 can be correlated with regulation of mTORC1 signaling in endometrial cancer tissues." (PMID 32899752, 2020). "We also investigated the role of SESN2 expression in endometrial cancer and the molecular mechanisms by which SESN2 regulates cancer cell growth and migration." (PMID 32899752, 2020). "Our results suggested SESN2 expression to be significantly upregulated in endometrial cancer tissues, correlating with an increased mTORC1 pathway." (PMID 32899752, 2020). "As ROS, hypoxia, inflammation, and ER stress are associated with cancer initiation and progression, it is plausible that these stresses contribute to the increased expression of SESN2 in endometrial cancer tissues." (PMID 32899752, 2020). "We evaluated the mRNA expression of SESN2 in the surgical endometrial cancer tissue samples and normal endometrium samples using quantitative real-time polymerase chain reaction (qRT-PCR)." (PMID 32899752, 2020). "Further, we performed Kaplan–Meier survival analyses to investigate the correlation of SESN2 expression with overall survival and disease-free survival in endometrial cancer patients." (PMID 32899752, 2020). "Consistent with the mRNA expression, immunoblot data showed SESN2 levels to be significantly more increased in endometrial cancer tissues than that in normal endometrial tissues." (PMID 32899752, 2020). "In summary, this study provided evidence for the prognostic significance and potential therapeutic role of SESN2 in endometrial cancer." (PMID 32899752, 2020). "Taken together, these results suggest that SESN2 expression affects the prognosis in endometrial cancer." (PMID 32899752, 2020). "This study aimed to investigate the expression and clinical implications of SESN2 in endometrial cancer using an in vitro and in vivo approach." (PMID 32899752, 2020). "The analysis suggested increased expression of SESN2 in endometrial cancer tissues, which correlates with high mTORC1 activity." (PMID 32899752, 2020).
endometrial cancer (continued). "SESN2 mRNA levels are significantly more elevated in endometrial cancer tissues than that in normal endometrial tissues." (PMID 32899752, 2020). "In this study, for the first time, we examined SESN2 expression levels in the primary tumors of endometrial cancer patients and in the endometrial cancer samples of The Cancer Genome Atlas (TCGA), and their correlations with clinicopathological factors." (PMID 32899752, 2020). "SESN2 expression strongly correlated with mTORC1 activity, suggesting its impact on prognosis in endometrial cancer." (PMID 32899752, 2020). "In the present study, we showed increased expression of SESN2 mRNA and protein in endometrial cancer tissues." (PMID 32899752, 2020). "SESN2 was found to regulate endometrial cancer growth, migration, and ROS production via the mTORC1-dependent mechanism." (PMID 32899752, 2020). "We also observed that knockdown of SESN2 enhanced tumor growth in endometrial cancer cells implanted in nude mice." (PMID 32899752, 2020). "In addition, SESN2 knockdown also enhances the proliferation and migration of endometrial cancer cells." (PMID 39388305, 2024). "The authors have speculated that elevated SESN2 protein level is induced upon chronic activation of mTORC1 in endometrial cancer cells." (PMID 37284849, 2023). "Interestingly, it was observed that SESN2 is upregulated in endometrial cancer (EC) tissue and correlated with shorter overall survival and disease-free survival in patients with endometrial cancer." (PMID 37284849, 2023). "Taken together, our results suggest that SESN2-mediated inhibition of mTORC1 might be one of the mechanisms responsible for therapeutic potential in endometrial cancer." (PMID 32899752, 2020). "We found that SESN2 knockdown enhanced mTORC1 activation in endometrial cancer cell lines." (PMID 32899752, 2020). "Additionally, immunohistochemistry staining results validated from the Human Protein Atlas database revealed the SESN2 protein to be downregulated in normal tissues and upregulated in endometrial cancer tissues." (PMID 32899752, 2020). "Thus, our study elucidates the relationship between SESN2, the mTORC1 pathway, and endometrial cancer growth, and defines SESN2 as a therapeutic target to inhibit the progression of endometrial cancer." (PMID 32899752, 2020). "A possible reason for the disagreement between patient and cell line data may be due to the bidirectional role of SESN2 in endometrial cancer progression." (PMID 32899752, 2020). "However, the relationship between growth and SESN2 expression has remained unanswered in endometrial cancer." (PMID 32899752, 2020). "The Kaplan–Meier analysis identified SESN2 as a putative prognostic factor in endometrial cancer." (PMID 32899752, 2020). "Moreover, knockdown of SESN2 promoted endometrial cancer cell proliferation, migration, and ROS production via the mTORC1-dependent pathway." (PMID 32899752, 2020). "However, clinical significance of SESN2 in endometrial cancer, and its role in the regulation of endometrial cancer cell proliferation and migration, remains unexplored." (PMID 32899752, 2020). "Thus, our study provides evidence for the prognostic significance of SESN2, and a relationship between SESN2, the mTORC1 pathway, and endometrial cancer growth, suggesting SESN2 as a potential therapeutic target in endometrial cancer." (PMID 32899752, 2020). "Moreover, the knockdown of SESN2 enhanced phosphorylation of S6 and p70S6K proteins, indicating SESN2 expression to negatively regulate mTORC1 activity in endometrial cancer." (PMID 32899752, 2020). "However, the molecular relationship between SESN2 and the mTORC1 pathway in endometrial cancer remained to be understood." (PMID 32899752, 2020). "Thus, the analysis suggests that the inhibitory effect of SESN2 on proliferation and migration of endometrial cancer cells is dependent on mTORC1." (PMID 32899752, 2020).